SPON2 (spondin 2)
Diseases named in the same sentence as SPON2 in open-access papers (continued):
Sharing a sentence is not in itself a finding about the gene and the disease.
lymph node metastasis (5 papers, 2015 to 2023). "Spondin-2 overexpression was significantly associated with well differentiation, depth of invasion, lymph node metastasis, and advanced TNM stages." (PMID 28060752, 2017). "Taken together, it was concluded that higher SPON2 protein expression, positive lymph node metastasis, and poor differentiation were significantly associated with poor overall survival (P <.001)." (PMID 28938639, 2017). "In recent years, SPON2 has been proved to promote cancer progression in many malignant tumors, such as by regulating Notch signaling pathway or activates integrin β1/Pyk2 axis to promote tumor migration and growth and is associated with lymph node metastasis." (PMID 36153414, 2022). "Meanwhile, higher SPON2 expression, poor differentiation, and positive lymph node metastasis predict a poor prognosis in pulmonary ADC patients." (PMID 28938639, 2017). "We found that differentiation, lymph node metastasis and SPON2 expression played independent roles in pulmonary ADC." (PMID 28938639, 2017). "The expression levels of spondin-2 were increasing in both prominent serosal invasion group and lymph node metastasis group." (PMID 28060752, 2017). "Kaplan–Meier survival analysis was used to calculate the SPON2 expression level, differentiation, and positive lymph node metastasis to correlate these with patient survival time." (PMID 28938639, 2017). "In addition, in order to evaluate the prognostic value of Spondin-2 in different subgroups, patients were stratified according to tumor size, depth of invasion, and lymph node metastasis." (PMID 28060752, 2017). "In order to investigate the correlation of SPON2 overexpression and survival of pulmonary ADC, in our study, high SPON2 protein levels were found to be associated with poor differentiation, positive lymph node metastasis and clinical stage by both univariate and multivariate analysis." (PMID 28938639, 2017). "The overexpression of Spondin-2 remained its prognostic value in predicting shorter OS and RFS in the subgroup of lymph node metastasis." (PMID 28060752, 2017). "Moreover, to evaluate the independent impact of spondin-2 overexpression on RFS and OS, a multivariate Cox regression model adjusted for tumor size, tumor site, depth of invasion, lymph node metastasis and spondin-2 expression was performed." (PMID 28060752, 2017).
diabetes (4 papers, 2013 to 2025). "This shows higher NK cell SPON2 expression occurs in a TGFβ “rich” NK cell suppressive microenvironment and diabetes is associated with higher PBMC IL15 and TGFβ expression in CAD patients." (PMID 39941136, 2025). "The data indicate an HCMV-seropositive-induced restriction of SPON2 expression and diabetes suppression of HCMV-seropositive-induced influence." (PMID 39941136, 2025). "This suggests a TGFβ-dependent mechanism of plaque remodeling by diabetes through suppression of adaptive NK cell frequencies and upregulation of SPON2 expression." (PMID 39941136, 2025). "We addressed if CADhigh patients, grouped by low or high C2 frequencies (C2low: 5.47–21.53%, n = 16; C2high: 21.63–56.75%, n = 16), and relative to diabetes status (C2low or C2high: diabetes−, n = 9; diabetes+, n = 7), display lower NK cell SPON2 expression and lower PBMC TGFβ transcript levels." (PMID 39941136, 2025). "Mx1 and Spon2 have had altered gene expression due to diabetes in any previous study." (PMID 24199937, 2013). "Therefore, we addressed if diabetes has a positive impact on NK cell SPON2 expression relative to CAD and HCMV status at the patient level [I: CADlowdiabetes− (n = 16), II: CADlowdiabetes+ (n = 13), III: CADhighdiabetes− (n = 18), and IV: CADhighdiabetes+ (n = 14)]." (PMID 39941136, 2025). "Additionally, diabetes-associated genes such as TXNIP, SPON2 and PAPPA were upregulated." (PMID 33923831, 2021). "Accordingly, as diabetes suppressed HCMV-induced adaptive NK cell frequencies, it enhanced PBMC TGFβ transcript and NK cell SPON2 expression." (PMID 39941136, 2025). "In CAD patients with higher stenosis severity, peripheral blood NK cell SPON2 expression was lower in patients with high HCMV-induced adaptive NK cell frequencies and corresponded to lower PBMC TGFβ transcript expression with dependency on diabetes status." (PMID 39941136, 2025).
adenoma (3 papers, 2015 to 2020). A neoplasm arising from the epithelium. "Among them, SPARC and SPON2 were down-regulated in adenoma and AEM, and up-regulated in AEC and advanced carcinoma." (PMID 33322258, 2020). "Immunohistochemistry for SPON2 showed similar pattern in adenoma and AEM, being positive in both epithelial cell and in the stroma." (PMID 33322258, 2020). "Some of these genes have already been reported in adenoma compared to carcinoma, such as SPON2, SPP1, and SPARC, which is validation for our own analysis." (PMID 30175151, 2018). "Moreover, SPON2 and SPARC showed up-regulation in AEC and advanced carcinoma, and down-regulation in adenoma and AEM." (PMID 33322258, 2020). "The aim of this study was to determine whether the expression of selected ECM-related genes (DCN, EPHA4, FN1, SPARC, SPON2, and SPP1) was similar in adenoma and AEM but differed from the expression in AEC and advanced carcinoma." (PMID 33322258, 2020).
glioma (3 papers, 2019 to 2021). A benign or malignant brain and spinal cord tumor that arises from glial cells (astrocytes, oligodendrocytes, ependymal cells). "In addition, we verified the association of SPON2 and IFI44 genes with macrophage recruitment and performed immunohistochemical staining on glioma samples for SPON2, IFI44, the macrophage marker CD68, and the M2 macrophage marker CD206." (PMID 34136486, 2021). "Combined with our experimental results, SPON2 may be involved in the recruitment of non-M2 macrophages in glioma." (PMID 34136486, 2021). "FUS/circ_002136/miR-138-5p/SOX13/SPON2 may aid in slowing the gliomagenesis in patients and provide an alternative strategy for glioma treatment." (PMID 30736838, 2019). "The immunostaining score evaluated by two professional pathologists showed that SPON2, IFI44, CD68, and CD206 were significantly overexpressed in high-grade gliomas." (PMID 34136486, 2021). "However, the function of SPON2 in vascular endothelial cells of glioma is still unknown." (PMID 30736838, 2019). "We performed immunohistochemical staining of SPON2, IFI44, CD68, and CD206 in 33 cases of gliomas." (PMID 34136486, 2021). "SPON2, IFI44, CD68, and CD206 were highly expressed in high-grade gliomas, and SPON2 was positively correlated with CD68 rather than CD206, whereas IFI44 was positively correlated with both CD68 and CD206 expression." (PMID 34136486, 2021).
lung adenocarcinoma (3 papers, 2022 to 2025). A carcinoma that arises from the lung and is characterized by the presence of malignant glandular epithelial cells. "The analysis of LOGpc further confirmed that the high expression of SPON2 was associated with the poor prognosis of early lung adenocarcinoma." (PMID 36153414, 2022). "In this study, an extracellular matrix protein SPON2 was found to be highly expressed in T1 stage lung adenocarcinoma and associated with poor prognosis by analysis of TCGA database." (PMID 36153414, 2022). "In this study, by deconvolution calculation of T1 stage lung adenocarcinoma in TCGA database, it was found that the expression of SPON2 was closely related to the infiltration of CAFs." (PMID 36153414, 2022). "Nevertheless, this was the first and preliminary study to find the role and potential regulatory mechanism of SPON2 in CAFs in progression of lung adenocarcinoma." (PMID 36153414, 2022). "Secondly, this study found that SPON2 can be derived from the exosome HOTAIRM1 of lung adenocarcinoma cells, which can affect the expression by competitive adsorption of miR-328-5p, so as to promote the invasion and metastasis of lung adenocarcinoma." (PMID 36153414, 2022). "It is a unique pattern recognition molecule of microbial pathogens in ECM and crucial in the initiation of innate immune response.In early studies, overexpression of SPON2 was confirmed to be an independent prognostic biomarker of lung adenocarcinoma." (PMID 36153414, 2022). "Definitive therapy targeting on SPON2 or HOTAIRM1 in tumor microenvironment may improve the therapeutic effect of lung adenocarcinoma." (PMID 36153414, 2022).
prostate tumor (3 papers, 2019 to 2025). "qRT-PCR validation in clinical samples confirmed significant overexpression of SPON2 (~18-fold) and MSMB (~2.6-fold) in prostate tumor tissues compared to matched normal tissues." (PMID 41200187, 2025). "The differential expression observed in the microarray analysis was further validated by qRT-PCR for two candidate secreted biomarkers, SPON2 and MSMB, using RNA extracted from prostate tumor tissues (n = 5) and their matched adjacent normal tissues (n = 5)." (PMID 41200187, 2025).
asthma (2 papers, 2016 to 2018). "Accumulated evidences support the role of SPON2 in production of pro-inflammatory cytokines, and development of airway hyper-responsiveness, which may contribute to the severity of allergic airways disease including asthma." (PMID 27518164, 2016). "In this study, several genes including Gdpd2, Spon2, Pon1, Scgb3a2, Ighv2-3, Sult1d1, Cyp2f2, Npas2, Arntl, and Igkv4-68 were down-regulated in OVA-challenged mice compared with control mice, may be useful as biomarkers of asthma." (PMID 29086354, 2018).
atherosclerosis (2 papers, 2020 to 2025). A disease characterized by the build-up of fatty material and calcium deposition in the arterial wall resulting in partial or complete occlusion of the arterial lumen. "Of note, SPON2 expression is up-regulated in the arteries in Apoe–/– mice fed with a Western diet to induce atherosclerosis compared to the control mice although the underlying mechanism remains unclear." (PMID 32974343, 2020). "Still, additional research is needed to investigate if NK cell SPON2 expression has a direct function on plaque vulnerability or stability or atherosclerosis outcomes such as acute coronary syndrome, myocardial infarction, or angina." (PMID 39941136, 2025). "Conversely, NK cell SPON2 expression was lower in pro-inflammatory atherosclerosis plaque tissue with an enriched adaptive NK cell gene signature." (PMID 39941136, 2025). "Moreover, NK cell SPON2 levels decreased in pro-inflammatory relative to pro-homeostatic atherosclerosis plaques, with the former showing an enriched adaptive NK cell gene signature." (PMID 39941136, 2025). "To investigate the clinical relevance of SPON2 in NK cells more specifically with relation to atherosclerosis, we examined SPON2 expression in pro-inflammatory carotid vs. pro-homeostatic femoral plaque tissue, in relation to IFNG and adaptive NK cell gene signature." (PMID 39941136, 2025). "Whether a similar mechanism accounts for SPON2-mediated macrophage migration in the context of atherosclerosis remains to be determined." (PMID 32974343, 2020). "Thus, blood NK cell SPON2 expression might have a value in diagnosis, prognosis, and therapeutical intervention in atherosclerosis." (PMID 39941136, 2025). "Although the validity of this conclusion awaits further authentication in animal models, this newly identified role for SPON2 certainly renews the argument that SPON2 neutralization by targeting Egr-1/BRG1 may be a reasonable approach when devising interventional strategies against atherosclerosis." (PMID 32974343, 2020). "Yet, the role of Spondin-2 in atherosclerosis in humans is not defined." (PMID 39941136, 2025).
bladder cancer (2 papers, 2020 to 2024). "Of more than 25 membrane proteins, only CXCR7, SPON2 and ANTXR1 had a significant difference in probability of survival in bladder cancer patients (only ∼10%)." (PMID 39917181, 2024). "The remaining 5 genes have not been found to be associated with the prognosis of bladder cancer (BTBD16, OLFML2B, PRRX1, SPINK4, and SPON2)." (PMID 33204728, 2020).
glomerular disease (2 papers, 2017 to 2023). "It will also be important to determine in future experiments whether podocyte/glomerular deletion of Spon2 has the ability to slow down glomerular disease progression." (PMID 29167507, 2017).
influenza (2 papers, 2018 to 2019). An acute viral infection of the respiratory tract, occurring in isolated cases, in epidemics, or in pandemics; it is caused by serologically different strains of viruses (influenzaviruses) designated A, B, and C, has a 3-day incubation period, and usually lasts for 3 to 10 days. "The top five genes of each of the two clusters (NK cell activity; NK and T‐cell activity) that were most closely correlated with influenza antibody titers had seven genes (SPON2, AKR1C3, PRF1, FCRL6, GZMA, CSTK, NKG7) which belong to the aging signature genes of IL‐7Rαlow EM CD8+ T cells." (PMID 31044512, 2019).
meningioma (2 papers, 2013 to 2015). A generally slow growing tumor attached to the dura mater. "Most of these genes were lowly expressed in both benign and malignant meningiomas; however, five genes (ADCY3, GAS7, LAG3, LRR32 and SPON2) showed a trend of elevated expression (>3 fold in mean values) in malignant meningiomas." (PMID 23349797, 2013).
osteoarthritis (2 papers, 2016 to 2022). A noninflammatory degenerative joint disease occurring chiefly in older persons, characterized by degeneration of the articular cartilage, hypertrophy of bone at the margins and changes in the synovial membrane. "SPON2 is considered a biomarker of osteoarthritis, since its expression was increased in synovial fluid of patients." (PMID 27518164, 2016). "Based on recent evidences that the SPON2 might be a biomarker of osteoarthritis and contribute to activation of innate immunity in allergic airways diseases, we validated its expression by qPCR that demonstrated an approximately 4-fold increase (p<0.001)." (PMID 27518164, 2016).
triple-negative breast carcinoma (2 papers, 2023 to 2025). An invasive breast carcinoma which is negative for expression of estrogen receptor (ER), progesterone receptor (PR), and human epidermal growth factor receptor 2 (HER2). "Spondin-2 (SPON2) is highly expressed in a variety of tumors and has been associated with poor prognosis, but the relationship to triple-negative breast cancer (TNBC) is unclear." (PMID 36959811, 2023).
acute lymphoblastic leukemia (1 paper, 2015). Leukemia with an acute onset, characterized by the presence of lymphoblasts in the bone marrow and the peripheral blood. "On the contrary, middle or high methylation of SPON2 promoter resulted in low expression of SPON2, which was strongly correlated with favorable outcome of patients with acute lymphoblastic leukemia." (PMID 25945835, 2015).
Astrocytoma (1 paper, 2023). "Besides this, SPON2 gene missense mutations caused by A269T changes were found in 1 instance of Astrocytoma and 1 case of STAD." (PMID 37713832, 2023).
atrophic gastritis (1 paper, 2020). "The levels of SPON2 in sera of patients with GC were significantly higher compared with those of healthy individuals and patients with atrophic gastritis." (PMID 31691494, 2020).
Autoimmunity (1 paper, 2020). The occurrence of an immune reaction against the organism's own cells or tissues. "Differential methylation of genes PIK3AP1 and SPON2 is not reported in association with other similar autoinflammatory diseases; however, PIK3AP1 was associated with autoimmunity, and its increased expression was shown to promote TLR7-driven lupus-like disease." (PMID 32793186, 2020).
breast fibroadenoma (1 paper, 2023). "Immunohistochemistry was used to detect the expression of the SPON2 protein in TNBC and in normal tissue adjacent to cancer and breast fibroadenoma." (PMID 36959811, 2023). "In this study, we demonstrated by immunohistochemical experiments that SPON2 protein expression was higher in TNBC tissues than in normal tissues adjacent to cancer and breast fibroadenoma." (PMID 36959811, 2023).
cardiac hypertrophy (1 paper, 2024). "Another member of the same family, SPON2 (mindin), appears to attenuate cardiac hypertrophy, fibrosis, and dysfunction in response to pressure overload or neurohormonal activation." (PMID 38225249, 2024).
colon adenoma (1 paper, 2015). An adenoma that arises from the colon. "Interestingly, SPON2 mRNA was gradually elevated from colon adenoma to CRC (n = 10, p = 2.1E-5) by analyzing Skrzypczak Colorectal 2 dataset." (PMID 25945835, 2015).
colorectal adenoma (1 paper, 2021). An adenoma that arises from the colon or rectum. "In addition, the SPON2 gene is significantly upregulated in CRC compared to colorectal adenomas." (PMID 33712897, 2021).
dengue (1 paper, 2022). "Of interest, we observed that several predictive genes of severe dengue, including GYG1, TOR3A, SPON2, GRAP2 and GBP2, were also highly transcribed in the ASCs and effector T cells at Day −1 in our dataset." (PMID 35345453, 2022).
diabetic nephropathy (1 paper, 2017). "It was recently shown that SPON2 mRNA expression increased in the glomerulus of diabetic mice and that SPON2 is excreted in the urine of patients with type-2 diabetes and diabetic nephropathy." (PMID 28938639, 2017). "Similarly, there is a linear and significant increase in SPON2 levels in type-2 diabetes patients as the stage of diabetic nephropathy increases, but serum SPON2 levels were not as reliable as that in urine and tissues in the detection of renal damage in diabetic nephropathy." (PMID 28938639, 2017).
diffuse large B-cell lymphoma (1 paper, 2023). "While SPON2 was expressed at lower levels in the tumor tissues of Lymphoid neoplasm diffuse large B-cell lymphoma and THYM than in normal tissues, we discovered that GBM, skin cutaneous melanoma, brain lower grade glioma (LGG), and TGCT showed greater expression in tumor tissues (P < .01)." (PMID 37713832, 2023).
gastric tumors (1 paper, 2017). "Based on these studies, SPON2 expressed differentially in ovarian, colorectal, prostate, and gastric tumors compared with that in respective normal adjacent tissue; therefore, we concluded that SPON2 protein might be used as a diagnostic biomarker and detected in the patient's blood." (PMID 28938639, 2017).
human papillomavirus infection (1 paper, 2023). "The most relevant signaling pathways for SPON2 are focal adhesion, ECM-receptor interaction, protein digestion and absorption, PI3K-Akt signaling pathway, human papillomavirus infection, proteoglycans in cancer." (PMID 36959811, 2023).
laryngeal squamous cell carcinoma (1 paper, 2024). A squamous cell carcinoma that arises from the larynx. "Similarly, high expression of SPON2 in laryngeal squamous cell carcinoma was associated with metastasis and higher pathological grade." (PMID 39917181, 2024).
leukemia (1 paper, 2017). A malignant (clonal) hematologic disorder, involving hematopoietic stem cells and characterized by the presence of primitive or atypical myeloid or lymphoid cells in the bone marrow and the blood.
lupus erythematosus (1 paper, 2021). An autoimmune, connective tissue chronic inflammatory disorder affecting the skin, joints, kidneys, lungs, heart, and the peripheral blood cells. "Spondin 2 (SPON2) was reported to be implicated in the integrin pathway, protein metabolism, and drug‐induced lupus erythematosus." (PMID 33998076, 2021).
metastasis (1 paper, 2020). The spread or migration of cancer cells from one part of the body (where they first appeared) to another. "However, serum levels of SPON2 in patients with advanced GC (n = 20) with liver or lung metastasis were significantly higher compared with those without such metastases (n = 63)." (PMID 31691494, 2020).